MAGEA2B (MAGE family member A2B)
Description:
Also represses p73/TP73 activity. Proposed to enhance ubiquitin ligase activity of RING-type zinc finger-containing E3 ubiquitin-protein ligases. Proposed to act through recruitment and/or stabilization of the Ubl-conjugating enzyme (E2) at the E3:substrate complex. May play a role in embryonal development and tumor transformation or aspects of tumor progression. In vitro promotes cell viability in melanoma cell lines. Antigen recognized on a melanoma by autologous cytolytic T-lymphocytes.
Synonyms: CT1.2; MAGEA2; MAGE2; MGC16973
Tractability: PROTAC: ubiquitination databases record sites on it.
Gene: Protein-coding gene on chromosome X (152,714,580 to 152,718,612, forward strand). Ensembl gene ENSG00000183305.
Subcellular location: Nucleus; Nucleus, PML body
Gene Ontology:
Molecular function: DNA-binding transcription factor binding; histone deacetylase binding; protein binding; ubiquitin protein ligase binding
Biological process: cellular senescence; negative regulation of protein acetylation; negative regulation of protein sumoylation; negative regulation of transcription by RNA polymerase II; positive regulation of ubiquitin-protein transferase activity; protein catabolic process
Cellular component: nucleus; PML body
Homologues: Orthologues: chimpanzee MAGEA2 (97% identical), mouse Magea13 (37% identical), rat Magea13 (35% identical), zebrafish ndnl2 (19% identical), Drosophila melanogaster MAGE (16% identical). Paralogues in human: MAGEA2 (100% identical), MAGEA12 (88% identical), MAGEA3 (84% identical), MAGEA6 (84% identical), MAGEA4 (68% identical), MAGEA1 (67% identical), MAGEA8 (63% identical), MAGEA9 (59% identical), MAGEA9B (59% identical), MAGEA11 (59% identical), MAGEA10 (52% identical), MAGEB16 (42% identical), and 25 more.